CD274 (CD274 molecule)
Diseases named in the same sentence as CD274 in open-access papers (continued):
Sharing a sentence is not in itself a finding about the gene and the disease.
tumor (continued). "It was reported that cancer cells mediate T cells polarization through PD-L1 (CD274) to down-regulate immunosurveillance and enhance tumor proliferation by releasing of TGF-β, IL-10, and other regulatory cytokines." (PMID 30699956, 2019). "PD-L1 (CD274) is regarded as an important mediator of T cell proliferation and PD-L1/PD1 signaling inhibits immune response and results in immune escape of tumor cell." (PMID 30961670, 2019). "Programmed death ligand 1 (PD-L1), also known as CD274, is considered an immune checkpoint facilitating anti-tumor suppression of the immune pathway." (PMID 30769852, 2019). "Interacting with two cell surface ligands, PD-L1 (CD274) and PD-L2 (CD273) expressing on immune cells or tumor cells, it inhibits T cell activation." (PMID 31134073, 2019). "The PD-1 receptor on T cells interacts with PD-1 ligands including PD-L1 (CD274) and PD-L2 (PDCD1LG2), on the surface of tumor cells." (PMID 31075138, 2019). "We identified an increased expression of genes that were previously found in the astrocytes from tumor specimens, (HLA-DRA, CHI3L1 SERPINA1, CCL18, CD37, and CD274)." (PMID 31186414, 2019). "Programmed cell death 1 ligand (PD-L1; also known as B7-H1, CD274) is an immune inhibitory receptor ligand that is expressed by cancer cells and cells in the tumor microenvironment." (PMID 30850589, 2019). "Programmed death ligand 1 (PD-L1, CD274) expressed on tumor and/or immune cells in the tumor microenvironment (TME) interacts with PD-1 on tumor infiltrating lymphocytes, attenuating effector T cell responses and allowing tumors to escape immune attack." (PMID 31730010, 2019). "Although as a group the IR tumours also had high expression of the negative regulators of immune response PDCD1 (PD-1), CD274 (PD-L1) and CTLA4 (CTLA-4), immunohistochemical expression of these markers was only observed in some cases." (PMID 30153845, 2018). "PD-L1, which is also named CD274 or B7H1, is one ligand of PD-1 that is expressed on various types of tumor cells." (PMID 30003113, 2018). "Several recent examples have demonstrated the potential for various types of oncolytic viruses expressing immune checkpoint inhibitors such as anti-PDCD1 (PD-1), anti-CD274 (PD-L1), and anti-CTLA4, as well as other anti-tumor antibodies." (PMID 28822103, 2018). "Immune checkpoint blockade therapies (ICBTs) targeting programmed cell death 1 (PD-1) and its ligand programmed death ligand-1 (PD-L1/B7-H1/CD274) have exhibited momentous clinical benefits and durable responses in multiple tumor types." (PMID 29910728, 2018). "AA-HCT116 cells also upregulate the expression of CD274 (PDL-1), a molecule whose expression on tumor cells mediates immunosuppression by inhibiting the activation of CTL and NK cells." (PMID 30263014, 2018). "Prior to being treated with combination therapy, the tumors showed a relatively low number of tumor-infiltrating CD8-positive T cells and limited expression of programmed death-ligand 1 (CD274; previously named PD-L1)." (PMID 29148538, 2018). "We observed upregulation of PD-Ligand 1 (PD-L1, also known as CD274) mRNA in tumor compared to control tissues." (PMID 29966370, 2018). "Another immunological checkpoint that facilitates tumor cell evasion involves the interaction between Programmed Death-1 (PD-1; CD279) and Programmed Death Receptor Ligand-1 (PD-L1; also known as CD274 or B7-H1)." (PMID 29988281, 2018). "Programmed cell death-1 (PD-1, CD279) and its ligands [either PD-L1 (B7-H1, CD274) or PD-L2 (B7-DC, CD273)] play a fundamental role in tumor immune escape by inhibiting effector functions." (PMID 29967612, 2018). "Within the inflammation-tumor microenvironment, CD274 and PDCD1LG2 play an important role in facilitating immune escape for tumor cells." (PMID 28286742, 2017).
tumor (continued). "With the facilitation of bioinformatics analyses and validation, we identified some tumor-related genes, such as NNMT, FLI1, GAS6, lncRNA CCAT1, PDCD1LG2, and CD274, as the key regulators in the present tumor-like transformation model." (PMID 28286742, 2017). "PD-1 is engaged by ligands PD-L1 (B7-H1, CD274) and PD-L2 (B7-DC, CD273), expressed by tumor cells and infiltrating immune cells." (PMID 29221220, 2017). "Programmed death receptor-ligand 1 (PD-L1; also known as B7-H1 or CD274) is known to play an important role in immune evasion of tumor cells." (PMID 28076847, 2017). "Immunohistochemically, few numbers of cells were positive for CD8 (1/1 dilution; Roche) and PD-L1/CD274 (clone SP142, 1/50 dilution; Spring Bioscience) expression was <1% in tumor-infiltrating immune cells and tumor cells." (PMID 29162045, 2017). "Programmed death ligand-1 (PD-L1), known as B7-H1 or CD274, is a glycoprotein of the B7 superfamily that is expressed on the cell surface of various tumor cells, as well as in lymphocytes, macrophages, and dendritic cells." (PMID 29259270, 2017). "We also observed that none of these ligands were downregulated by IFNγ; however, CD274/PD-L1, CD54/ICAM-1, HLA-DR, MHC-class I, CD95/FasR, and CD270/HVEM were upregulated in a variety of tumor types." (PMID 28428785, 2017). "The PD-1 ligands such as PD-L1 (CD274) and PD-L2 (CD273) are B7 family members and are known to be overexpressed on the surface of tumor cells where they block cytotoxic T cells." (PMID 27050074, 2016). "Appreciation of the genetic and immunologic landscape of these aggressive NHL, including PD-L1 (B7-H1, CD274) expression by malignant T cells and within the tumor microenvironment, provides a strong rationale for therapeutic targeting this immune checkpoint." (PMID 28031823, 2016). "In the model of adaptive immune resistance IFNγ-driven expression of PD1 ligands CD274 and PDCD1LG2 on tumour cells and the microenvironment limits local T-cell responses." (PMID 26362649, 2015). "This receptor binds to its ligand PD-L1 (or B7-H1 or CD274) and PD-L2 (or B7 DC or CD273) which are expressed in tumor cells and antigen presenting cells." (PMID 26487966, 2015). "When tumour-transplanted mice were sacrificed due to overt CLL, we again observed a trend for increased CD274 levels, which was most prominent on lymph node-residing CLL cells (Fig2; MFIR 17·2 ± 17·1, P = 0·003)." (PMID 25940792, 2015). "The primary function of PD-1 is in peripheral tissue where T-cells encounter immunosuppressive ligands PD-L1 (also known as B7-H1 or CD274) and PD-L2 (also referred to as B7-DC or CD273) which are expressed by tumor and/or stromal cells." (PMID 23515890, 2013). "B7-H1 (PD-L1, CD274) is a T cell inhibitory molecule expressed in many types of cancer, leading to immune escape of tumor cells." (PMID 20626886, 2010). "For immune checkpoint inhibitors, a pre‐existing inflamed tumor microenvironment, characterized by high CD8+ tumor‐infiltrating lymphocytes and inflammatory gene signatures (e.g., CD8A, CD274, LAG3), correlates with improved survival with nivolumab and atezolizumab plus bevacizumab." (PMID 41509174, 2026). "Hypermethylation frequency of NTSR1 in CAC versus normal tissue (p = 0.037)Half of the CACs (16/31, 52%) expressed CD274-positive immune cells, whereas tumor cells were CD274-negative." (PMID 41562706, 2026). "Moreover, AMIGO2 expression positively correlates with CD274 (PD-L1) in PAAD, suggesting a possible link to immune-evasive tumor microenvironments and checkpoint activation." (PMID 41583520, 2026). "Conversely, downregulated genes included CD274 (PD-L1), TGFB1, and TGFBR1, which may reflect reduced transcriptional signatures of immune suppression within the tumor microenvironment." (PMID 41596590, 2026). "Moreover, the FUSCC dataset (SRP157974) was used again to compare further characteristics, such as tumor stage, PDCD1, and CD274, in the FAM114A1-high/low patient groups." (PMID 41249116, 2025).
tumor (continued). "Moreover, our transcriptomic data further revealed that lacidipine regulated multiple immune‐related genes, significantly upregulating “hot” tumor‐related genes such as CCL5, CD274, CXCL10, and CXCL11, while downregulating the “cold” tumor‐related gene CCL2." (PMID 39585774, 2025). "Additionally, tumour cell-secreted Gal1 was also reported to induce M2 phenotype in TME during the early stages, with the activation of immune checkpoints including PD-L1/CD274 and IDO1." (PMID 40507367, 2025). "In tumor cells, CDK5 expression is crucial for IFNγ-induced CD274 expression." (PMID 41041338, 2025). "In addition, immune checkpoint molecules PD-1 (PDCD1), PD-L1 (CD274), and CTLA4 mediate tumor immune escape by suppressing the activity of immune cells and are known potential targets for RC immunotherapy." (PMID 40963625, 2025). "However, in the case of tumor cell-induced CD4+ Tex, the replacement of SMARCA2 by SMARCA4 leads to increased CD274 expression." (PMID 40342423, 2025). "Moreover, GEPIA data indicated that PRC1 had a positive expression correlation with ICD markers, including CD274 (PD-L1), CALR (CRT), and HMGB1 in tumor tissues from COAD and READ patients." (PMID 40847353, 2025). "We discovered that chemotherapy reshaped the tumor immune microenvironment, evident through the reduction in human leukocyte antigen (HLA) diversity and the increase in PDCD1/CD274 in CD8_ANXA1, LAMP3+ dendritic cell (DC_LAMP3), and EREG+ monocytes (mono_EREG)." (PMID 40725006, 2025). "Moreover, EGF-driven EGFR activation also up-regulated CD274, suggesting a role for HER family signaling in promoting immunosuppression within the tumor microenvironment." (PMID 40642068, 2025). "Further dissection of immune cell-type correlations provided additional insight into how PSD3, CD274, and TNFSF18 may shape the tumor immune microenvironment (TME) in ESCC." (PMID 40895529, 2025). "In particular, our analysis revealed increased expression of various immune modulatory molecules (CD274 (PD-L1), OSM, PTGES2, CD36, and MSR1) by tumor-infiltrating monocytes and neutrophils suggesting an immune suppressive role is adopted following infiltration into the TME." (PMID 39932553, 2025). "On these bases, we moved to large‐scale MIF analyses and stained 326 samples from 292 patients for the expression of CD8 (tumour infiltrating T cells), CD68 (tumour infiltrating monocyte/macrophages), cytokeratins (tumour cells), and nuclei, along with CD274 (PD‐L1)." (PMID 40545725, 2025). "CXCL12 correlated with CD274 (R = 0.369) and PDCD1 (R = 0.288); CXCR4 correlated with CD274 (R = 0.579) and PDCD1 (R = 0.520), suggesting their roles in regulating immune checkpoints and tumor immune escape." (PMID 41142306, 2025). "Nevertheless, effective tumor immunosuppression is not achieved by inhibiting PD-1/CD274 (PD-L1) in conjunction with T cell reduction and/or malfunction in TME." (PMID 40161493, 2025). "Importantly, the authors also demonstrated that tumour-related genes, such as NNMT, FLI1, GAS6, lncRNA CCAT1, PDCD1LG2, and CD274, were key regulators of neoplastic transformation in response to a low multiplicity of oral pathogen infection." (PMID 41228271, 2025). "Although this blocking effect did not affect Arg1 expression in TMZ-resistant GBM tumor, blocking IL-19 still can downregulate the expression of STAT3-associated immunosuppressive genes (CD274 and S100A4) in both TMZ-sensitive and TMZ-resistant GBM tumor." (PMID 40057744, 2025). "Furthermore, significant differences in the expression of immune checkpoints—specifically CD200, CD274 (PD-L1), TIGIT, TNFRSF25, and TNFSF15—were observed between tumor and normal samples." (PMID 40666524, 2025). "Of note, BI-5756 did not affect the expression of CD274 (PD-L1), an immune checkpoint ligand that enables tumor immune evasion through the engagement of PD-1 on immune cells." (PMID 40942043, 2025).
tumor (continued). "According to our results, IL33 did not directly increase the protein expression of PD-L1 or CD274 in tumor cells." (PMID 41214328, 2025). "Since immune checkpoints can fuel tumor immunotherapy, we also evaluated the correlation of TMEM115 with the common immune checkpoints, the results showed that TMEM115 was correlations with CD274 (PD-L1) (R = 0.15, P = 2.7e-11)." (PMID 40552281, 2025). "The results showed that CD200, CD80 and TNFRSF14 were the highest in tumor tissues, CD274 (PDL1), CD86, LGALS9, NECTIN2, PDL2, PVR were lower than those in adjacent tissues but higher than those in normal tissues, and FGL1 was the lowest in tumor tissues." (PMID 39120585, 2024). "The results indicated that the mRNA expression levels of BCLAF1 were positively correlated with PD-L1 (CD274), and consistent findings were obtained using Tumor Immune Estimation Resource (TIMER) database and Gene Expression Profiling Interactive Analysis (GEPIA) database based on TCGA analysis." (PMID 38340178, 2024). "On the PD-L1 side of the axis, we found expression of the PD-L1 gene (CD274), PD-L1+ immune cells (in particular macrophages), and the PD-L1 CPS, but not PD-L1+ tumor cells or the PD-L1 TPS associated with pCR in the overall cohort." (PMID 39510069, 2024). "High MAEL expression was associated with few CD8+ T cells in tumor center (P=0.040), tumor margin (P=0.016), and total area (P=0.026), high TMB (P=0.013), and low expression of PDCD1 (P=0.003) and CTLA4 (P=0.049) rather than CD274 (P=0.12)." (PMID 38301040, 2024). "Among these, CD273 and CD146 may indeed be MSC-specific, whereas CD36 (a receptor for thrombospondin-1), CD200 (also expressed on tumor cells), CD274 (PDL-1), and CD248 (endosialin) are also expressed in fibroblasts, often in a tumor context." (PMID 39201399, 2024). "It is reported that HIF-1α could result in tumor immune escape from CD8+ cells by transactivating CD274 and upregulating the expression of PD-L1." (PMID 38713276, 2024). "Similarly, in KIRP SIGLEC12 positive tumours, a weak positive correlation in PDCD1 (Fig. 4C1), CD274 (Fig. 6C2), CTLA4 (Fig. 6C3), IL-2 (Fig. 6C4) was observed." (PMID 38268823, 2024). "Together with the trending increase in CD274 expression, our results may indicate that KMT2DLOF MSI COAD/READ cancers have increased T-cell infiltration and anti-tumour immune cell activity compared to KMT2DWT MSI cases." (PMID 39578878, 2024). "In our study, we found that high PSMB2 expression may induce the upregulation of CD274, CTLA4, HAVCR2, LAG3, PDCD1, PDCD1LG2 and SIGLEC15, which are molecules on immune cells that facilitate tumor immune escape." (PMID 38467767, 2024). "NT5E (CD73), CSF ligands, CD274 (PDL1), IL1B, IL6, and IL10 transcripts were primarily found in the peri necrotic zone, whereas NOS2 (iNOS), TGFB2, and NOX1 expression is localized to cellular tumor regions." (PMID 39272914, 2024). "We looked examined the connection between CD274 expression and DSS (disease-specific survival) in 33 malignancies because non-tumor-related variables could lead to death in the time of the follow-up." (PMID 38166842, 2024). "Low TPS results revealed significantly changed pathways involving tumour–non-cancerous cell interactions, such as PD-L1/PD-1 (CD274 on tumour cells and PDCD1 on T cells) and Galectin-9/TIM-3 (LGALS9 on tumour cells and HAVCR2 on immune cells)." (PMID 39457550, 2024). "CD274 expression (gene for PD-L1) was not significantly higher among tumor cells in this study; however, PD-L1 has also not been shown to be a reliable biomarker for immunotherapy response in ccRCC." (PMID 39639369, 2024). "However, to our surprise, our results demonstrated that EPHX4 was significantly negatively correlated with CD274, PDCD1, IDO1 and LAG3, which all attenuate anti-tumor immunity and escape destruction by the immune system." (PMID 38663041, 2024).
tumor (continued). "The PD-L1 (also known as CD274) expressed by tumor cells plays a crucial role in the mediation of immunosuppression, and its expression level in tumor cells has a potential relationship to objective response of immunotherapy of ccRCC, such as anti-PD1 inhibitors." (PMID 38671348, 2024). "We found that the expression of PD-1 (PDCD1/CD279) was lower in ESCA samples and that the differences in the corresponding ligand (tumor cell) CD274 (PD-L1) were non-significant across patients and groups." (PMID 39076970, 2024). "Biomarkers of immune checkpoint inhibitor therapy reported include PD‐L1, ratio of tissue‐resident memory T cells to depleted CD8+ T cells in the tumor microenvironment, regulatory T cells, 11‐gene signature, high expression of CD274, T‐effector signature, and intertumoral CD8+ T cell density." (PMID 38577725, 2024). "Based on a study, tumor cells overexpressed CD47 and PD-L1 (CD274) to evade immune cell clearance." (PMID 39256364, 2024). "Programmed death receptor-1 ligand (PD-L1, CD274), which serves as a ligand for programmed death receptor-1 (PD-1), is predominantly expressed on the membrane surface of monocytes, macrophages, dendritic cells and various tumor cells." (PMID 39668828, 2024). "However, CD274/PD-L1, CD54/ICAM-1, HLA-DR, MHC class I, CD95/FasR, and CD270/HVEM are regulated in various tumour types." (PMID 38748263, 2024). "The CellphoneDB analysis of ligand-receptor pairs showed that the interaction networks between UPP1high tumor cells and FOXP3+ Tregs/LAG3 + PDCD1 + CD8 + T cells were involved with numerous immune checkpoints, including CD274/PDCD1LG2_PDCD1, FGL1_LAG3, and NECTIN_TIGIT." (PMID 38331898, 2024). "This eventually masked the impact of immune escape in RE tumours, as expression of checkpoint molecules CD274 (PD-L1; programmed cell death ligand 1) and CD152 (CTLA-4; cytotoxic T-lymphocyte-associated protein 4) were found to be markedly increased at baseline levels." (PMID 37460712, 2023). "Additionally, a strong correlation between RHBDF2 upregulation and immune checkpoint genes (PDCD1, CD274, LAG3, CTLA4, TIGIT, HAVCR2) was observed in HCC, and these immune checkpoint genes can contribute to tumor immune escape and promote tumor progression." (PMID 36943228, 2023). "Furthermore, KLRB1 expression levels are significantly correlated with tumor purity, immune infiltration, and immunotherapy-related markers such as PDCD1, CD274, and CTLA4." (PMID 37988189, 2023). "When comparing tumor samples with non-tumor samples, we did not observe significant differences in the percentage of monocyte subpopulations expressing CD274 or CD206." (PMID 37370832, 2023). "Analysis of RNA from CD45+ tumor infiltrating cells isolated from Kin1-WT and Kin1-NULL tumors was carried out which showed a reduction of various T cell inhibitory checkpoint pathway related genes, including Cd274, Vsir and Havcr2 in Kin1-NULL tumors." (PMID 36883731, 2023). "Interestingly, we observed a decrease in the percentage of all monocyte subpopulations expressing CD274 and CD206 in tumor samples with a desmoplastic growth pattern compared to non-desmoplastic." (PMID 37370832, 2023). "Interestingly, in most tumor types, immunosuppression-related genes, especially TGFBR1 and PD-L1 (CD274), exhibited a specific correlation with the ORC6 expression." (PMID 36978046, 2023). "Accordingly, this study revealed that non-hematopoietic cells presented significantly decreased CD274 expression on tumor samples from CRCLM patients compared to non-tumor samples." (PMID 37370832, 2023). "Belonging to the immunoglobulin super family, PD-1 is a transmembrane coinhibitory receptor primarily expressed on the surface of activated T cells and NK cells as the ligands to PD-1, PD-L1 (B7-H1 or CD274), and PD-L2 (B7-DC or CD273) are expressed on the surface of tumor cells." (PMID 37025485, 2023).